RNU6-185P (RNA, U6 small nuclear 185, pseudogene)
Gene: Small nuclear RNA gene on chromosome 15 (87,474,183 to 87,474,289, reverse strand). Ensembl gene ENSG00000207150.
Homologues: Orthologues: chimpanzee U6 (99% identical), macaque U6 (89% identical), mouse Gm26159 (74% identical), dog U6 (69% identical). Paralogues in human: RNU6-21P (86% identical), RNU6-463P (85% identical), RNU6-1 (84% identical), RNU6-1263P (84% identical), RNU6-15P (84% identical), RNU6-2 (84% identical), RNU6-207P (84% identical), RNU6-33P (84% identical), RNU6-3P (84% identical), RNU6-4P (84% identical), RNU6-552P (84% identical), RNU6-5P (84% identical), and 1287 more.